VDR (vitamin D receptor)
Diseases named in the same sentence as VDR in open-access papers (continued):
Sharing a sentence is not in itself a finding about the gene and the disease.
osteoporosis (continued). "The VDR gene is polygenetic gene, and single nucleotide polymorphisms (SNPs) of VDR gene could influence the expression and function of VDR protein, which are proved to influence the risk of BMD and osteoporosis." (PMID 25784778, 2015). "Our data provide more evidence to support that the VDR genetic variants could influence the development of BMD and osteoporosis." (PMID 25784778, 2015). "In Spain, 719 postmenopausal women were genotyped for common VDR polymorphisms, and a lack of relevance for osteoporosis and these polymorphisms was found." (PMID 26157644, 2015). "Genes hypothesized to play a role in osteoporosis include those involved in bone formation and remodeling (e.g., LRP5), those involved in hormone signaling (e.g., VDR and ESR1), and those that encode bone structure proteins (e.g., COL1A1)." (PMID 26393357, 2015). "Additionally, calcitriol, a VDR agonist, is also used to treat osteoporosis." (PMID 39997045, 2025). "Consequently, we suggest that targeting VDR signaling may be a potential therapeutic approach for HFD-induced BMSC senescence as well as osteoporosis and other HFD-related diseases." (PMID 38777841, 2024). "Therefore, vitexin’s apparent interaction with the VDR/eNOS signaling pathway and the subsequent effects on angiogenesis-dependent osteogenesis further solidifies vitexin’s potential as a novel therapeutic strategy for osteoporosis." (PMID 38318147, 2024). "They found that VDR FokI gene polymorphism did not significantly correlate with osteoporosis (OR = 1.17, 95% CI = 0.76–1.80) and that other loci on the VDR gene did not significantly correlate with osteoporosis." (PMID 35452412, 2022). "In addition, a number of candidate genes have been investigated (COL1A1, TGFB1, TGFB3, and VDR), but no clear genome-wide significant association with osteoporosis has been demonstrated." (PMID 35069689, 2021). "Finally, the Hardy–Weinberg equilibrium (HWE) test was not performed in the three studies, and not all studies on the VDR polymorphisms with osteoporosis fracture risk adjusted the P-value." (PMID 35069689, 2021). "Moreover, due to the limited number of studies, we did not perform subgroup analyses in the pooled analysis of VDR Cdx2 polymorphism and osteoporosis risk." (PMID 32627819, 2020). "Although the sample size of this study may have been relatively small, our results suggest that the interaction of the CG/CC genotype of VDR rs3782905 with TNF-α rs1800629 GG genotype was associated with increased odds of overall and lumbar spine osteoporosis in elderly women." (PMID 31887189, 2019). "In this study, we examined the interaction between VDR gene and TNF-α gene on osteoporosis in Chinese elders in Taiwan to determine whether or not VDR gene is associated with the regulation of immune functions." (PMID 31887189, 2019). "Therefore, we hypothesize that the p.Gly14Ala and p.His305Gln genetic variants of VDR gene play similar functions in the development of BMD and osteoporosis." (PMID 25784778, 2015). "Results from this study suggest that the VDR p.Gly14Ala and p.His305Gln genetic variants are significantly associated with BMD decrease in Chinese postmenopausal women and might be used as molecular markers for assessing the risk of BMD and osteoporosis." (PMID 25784778, 2015). "In the past, research has mainly focused on few candidate genes, namely the VDR, estrogen receptor alpha (ER-α) and COL1A1 genes, which have been investigated with regard to response to osteoporosis-drugs." (PMID 33162933, 2020). "The present study aims to evaluate the independent and interactive effects of SNPs in VDR and TNF-α genes on BMD and osteoporosis in elders from the Taichung Community Health Study for Elders (TCHS-E) in Taichung City, Taiwan." (PMID 31887189, 2019). "In recent years, the vitamin D receptor (VDR) gene has been considered as an important candidate gene in the modification and the development of BMD and osteoporosis." (PMID 25784778, 2015).
osteoporosis (continued). "Growing evidence supports that the VDR gene is one of the most important candidate genes in the modification of BMD metabolism and the pathogenesis of osteoporosis." (PMID 25784778, 2015). "These two genetic variants might be linked to other VDR genetic variants (such as Fok I (rs10735810), BsmI (rs1544410), and ApaI (rs7975232)) which have been proved to affect the function of VDR protein and contribute to influence the development of BMD and osteoporosis." (PMID 25784778, 2015). "Furthermore, our previous research has shown that by adjusting the mRNA expression of vitamin D3 receptor (VDR), QEF is capable of activating bone metabolism to prohibit further loss of bone mass, thereby preventing the bone deterioration observed to occur during osteoporosis." (PMID 26205885, 2015). "Various vitamin D receptor (VDR) gene variants have been studied and associated with osteoporosis in other populations, but not in a homogenous Arab ethnic group." (PMID 34698098, 2021). "Last, because of some technical limitations, we did not test the biomarkers of osteoporosis and VDR, which should be considered in future studies." (PMID 30962270, 2019). "However, no prior study has explored the independent and interactive effect of the genetic variation of VDR and TNF-α genes on BMD and osteoporosis." (PMID 31887189, 2019). "Statistical analysis in the group of women with osteoporosis (OPO) and in the control group of women (CG) did not confirm significant differences between the genotypes of the VDR gene BsmI polymorphism in relation to the anthropometric, densitometric, or biochemical parameters studied." (PMID 40149488, 2025). "For example, the vitamin D receptor (VDR), collagen type I (COL1), estrogen receptor (ER), apolypoprotein Е (ApoE), bone morphogenetic protein (BMP), and Low-density lipoprotein receptor-related protein 5 (LRP5) are all involved in the pathogenesis of osteoporosis." (PMID 38098042, 2023). "The VDR rs2228570 genotyping (FokI) could not predict RA disease from control (AUC 0.43, 95% CI 0.32–0.53; p = 0.15) or patients with and without osteoporosis (AUC 0.48, 95% CI 0.37–0.6; p = 0.8)." (PMID 35048212, 2022). "Analysis of genetic variants of the vitamin D receptor (VDR) concerns their relationship with metabolic bone diseases, and the results of previous studies assessing the relationship of polymorphisms with bone mineral density, fracture risk, or osteoporosis are not clear." (PMID 39859195, 2025). "More cases were required for the remaining six gene loci, namely, ESR1 PvuII (rs2234693), VDR ApaI (rs7975232), VDR BsmI (rs1544410), COL1A1 1997GT (rs1107946), ESR1 G2014A (rs2228480), and ESR2 AluI (rs4986938), before a definite conclusion could be made on their correlation with osteoporosis." (PMID 35452412, 2022). "The aim of the study was to ascertain whether there is an association between polymorphisms and single alleles of BsmI, ApaI, TaqI of VDR gene with BMD and the prevalence of vertebral/non-vertebral fractures in a group of postmenopausal women with osteoporosis." (PMID 23070909, 2013).
colitis (133 papers, 2007 to 2025). Inflammation of the colon. "In these studies, VDR-deficient mice also developed more severe colitis and had higher mortality rates when compared to VDR-sufficient mice." (PMID 40243631, 2025). "VDR deficiency is linked to more severe colitis and an increased risk of developing colorectal cancer." (PMID 40791849, 2025). "Studies with mice in the dextran sodium sulfate-induced colitis model showed an increase in mucosal permeability in VDR-deficient mice through the observation of reduced transepithelial electrical resistance (TER) levels." (PMID 40243631, 2025). "In VitD-deficient and VDR−/− colitis mice, NHE8 expression was compromised with more serious mucosal damage." (PMID 38004229, 2023). "We first examined the activation of NF-κb p65 signaling in VitD-deficient and VDR−/− colitis mice by detecting the nuclear location of pp65." (PMID 38004229, 2023). "In summary, our in vivo and in vitro data recapitulated that depressed NHE8 expression was responsible for VitD deficiency and VDR suppression-induced colitis aggravation." (PMID 38004229, 2023). "The protective effect of intestinal VDR against colitis is associated with expression of the VDR target gene Cldn15, which encodes the tight junction protein claudin-15." (PMID 36834927, 2023). "Overexpression of intestinal epithelial VDR resulted in significantly increased claudin-15 and decreased susceptibility to chemically and bacterially induced colitis." (PMID 35406694, 2022). "In the case of DSS-induced colitis, the deletion of the VDR renders a hypersensitivity to the agent and a vitamin D deficiency leads to an impaired antimicrobial gut response and increased colitis predisposition." (PMID 35625724, 2022). "It has been reported that loss of VDR in intestinal epithelial or myeloid cells will facilitate mucosal pro-inflammatory cytokine expression and exacerbate experimental colitis." (PMID 35444617, 2022). "Supplementing SPF mice with inadequate diet and nutrition with a specific combination of primary or secondary bile acids can increase the proportion of colonic Treg cells via the bile acid-VDR axis and reduce the susceptibility to colitis." (PMID 36522791, 2022). "Our studies further demonstrated that mice with conditional deletion of intestinal epithelial VDR are susceptible to colitis, due to dysbiosis, dysfunction of Paneth cells, dysregulated autophagy, and disrupted TJs." (PMID 35406694, 2022). "Compared with the VDR-KO control group, the VDR-KO colitis group (KO + DSS) showed obvious weight loss, shortened colon." (PMID 35711312, 2022). "In keeping with this, colitis-prone IL-10-deficient mice exhibit a decline in vitamin D receptor (VDR) expression that correlates with colitis symptoms." (PMID 33042125, 2020). "In order to further clarify, which member of the vitamin D/VDR pathway was actually causing those changes, we tested the effect of vitamin D status on oxazolone-induced colitis in WT mice." (PMID 32541827, 2020). "VDR KO mice have a higher susceptibility to DSS-induced colitis and subsequent dysbiosis with fewer butyrate-producing bacteria and increased E. coli and Bacteriocides." (PMID 32422882, 2020). "Deletion of VDR (VDR KO) in mice increases the susceptibility to DSS-induced colitis by inducing severe diarrhoea, rectal bleeding, and marked body weight loss, leading to death in 2 weeks when compared with normal animals." (PMID 32340206, 2020). "Vitamin D protects against colitis through VDR by regulating the gut microbiota and decreasing pathogenic infections in the colon." (PMID 32422882, 2020). "Treatment with the VSL (a probiotic including eight different strains of bacteria) has meaningfully raised the VDR expression in the proximal and distal colons in a rat model of colitis-associated cancer." (PMID 31231490, 2019). "Vitamin D and or vitamin D receptor (VDR) deficiency increases the susceptibility of mice to several different models of experimental colitis." (PMID 31417552, 2019).
colitis (continued). "In a mouse model of Salmonella infection, Salmonella inhibits the expression, distribution, transcriptional activity, and target gene expression of VDR, resulting in elevated NF-κB activity in the mucosa and increased susceptibility to colitis." (PMID 30804707, 2019). "Sequencing of fecal DNA from Cyp27B1 KO and VDR KO mice showed increased frequencies of Proteobacteria and colitis causing Helicobacteraceae family members." (PMID 29599772, 2018). "Previously reported rodents with increased susceptibility to DSS colitis have included vitamin D receptor- and Cyp27B1- KO mice." (PMID 30065252, 2018). "The increased susceptibilities of Cyp27B1 KO and VDR KO mice to colitis were shown to be caused in part by shifts in the composition of the gut microbiota in mice." (PMID 29599772, 2018). "Vitamin D receptor (VDR) deficiency resulted in severe inflammation of the gastrointestinal tract in IL-10 KO mice which spontaneous develops colitis." (PMID 26790152, 2016). "To investigate the role of p21 in maintaining mucosal epithelial homeostasis in AMP-mediated protection of epithelial cells in vivo, we studied expression of p21 in TNBS-induced colitis in vitamin D receptor (VDR)-deficient (VDR-/-) mice." (PMID 25919700, 2015). "Genetic VDR deletion in mice is associated with normal histology but leads to increased vulnerability to TNBS- or DSS-induced colitis." (PMID 25919700, 2015). "These mice had an increased susceptibility to dextran sulfate sodium (DSS) colitis, whereas in human colon samples of low VDR expression correlate with ATG16L1 and a reduction of Bacteroides species." (PMID 26000293, 2015). "The more severe colitis was associated with rapidly proliferating naïve VDR KO CD8+ T cells and increased IFN-γ and IL-17 in the gut." (PMID 24502291, 2014). "VDR deficient mice are extremely sensitive to intravenous or intraperitoneal administration of LPS, supporting the possibility that VDR KO mice with colitis die due to endotoxemia." (PMID 17397543, 2007). "The effectiveness of 1,25(OH)2D3 in protecting the colon and the heightened susceptibility of the VDR KO gut to DSS colitis is likely due in part to the importance of vitamin D and VDR signaling in control of epithelial growth and proliferation." (PMID 17397543, 2007). "VDR KO mice were extremely sensitive to dextran sodium sulfate (DSS) and there was increased mortality of the VDR KO mice at doses of DSS that only caused a mild form of colitis in wildtype (WT) mice." (PMID 17397543, 2007). "The shift from colitis to colorectal cancer is a major pathogenic role that VDR inhibits." (PMID 40725244, 2025). "The previous study showed EGF receptor‐VDR cross‐talk in colitis‐associated colon cancer." (PMID 40697702, 2025). "Our team has previously shown that administration of Vivomixx probiotic over a 3-month period increases VDR expression in a rat colitis-associated colorectal cancer model, suggesting that VDR upregulation may require prolonged exposure to the probiotic." (PMID 40944110, 2025). "This hypothesis is in line with findings from Lu, Y, who demonstrated that Monotropein could inhibit colitis-associated cancer through the VDR/JAK1/STAT1pathway, influencing macrophage polarization." (PMID 39513122, 2024). "In a study using a mouse model of colitis-associated cancer, treatment with asperuloside was found to significantly enhance the expression of VDR in the colon, leading to marked reductions in colitis symptoms and a decrease in both the quantity and size of tumors." (PMID 38318147, 2024). "Furthermore, except for colitis deterioration, VDR deletion also caused a dramatic reduction in NHE8 expression compared with wild-type colitis mice." (PMID 38004229, 2023). "The positively correlated status of VDR and claudins, such as claudin-5 and -15, could be potentially applied to risk assessment, early detection, and prevention of colitis and colitis-associated colon cancer." (PMID 35406694, 2022).
colitis (continued). "In SPF mice with insufficient diet and nutrition, the intestinal bile acid pool was restored (replenishing a specific combination of primary or secondary bile acids), colon RORγ+ Tregs were increased through the bile acid-VDR axis, and the susceptibility to colitis was reduced." (PMID 35265068, 2022). "The chemoprotective effects of mesalamine, as well as vitamin D and the VDR, on the development of colitis-associated colon cancer may be mediated through alterations in the gut microbiome." (PMID 35889090, 2022). "Furthermore, in a conditional intestinal epithelial VDR-overexpressed mouse model, we found the protective role of VDR in the maintenance of TJs in the context of inflammation and colitis-associated colon cancer." (PMID 35406694, 2022). "The VDR KO mice had impaired colonic antibacterial activity and were predisposed to colitis." (PMID 36076980, 2022). "VDR knockout and vitamin D-deficient mice displayed epithelial barrier dysfunction with hyperfunction of claudin-2, decreased transepithelial resistance, and increased susceptibility to invasive bacteria colonization and colitis." (PMID 33671090, 2021). "VDR knockout and vitamin D-deficient mice showed epithelial barrier impairment with hyperfunction of claudin-2, and increased susceptibility to invasive bacteria colonization and colitis." (PMID 34899302, 2021). "In mouse models, 1,25(OH)2D3 deficiency or VDR knockout increased the risk of colitis." (PMID 30828386, 2019). "Intestine epithelium-specific VDR knockout mice are also more susceptible to DSS-induced colitis." (PMID 30060580, 2018). "Cyp27B1 knockout (KO) and VDR KO mice were extremely susceptible to colitis." (PMID 29599772, 2018). "Further, vitamin D receptor (VDR) knock-out mice had more severe Salmonella infection than their wild-type counterparts and dietary-induced vitamin D-deficient mice had more severe inflammation and significantly higher bacterial load in a model of colitis." (PMID 28749951, 2017). "In experimental animal models, VDR knockout (VDR KO) mice showed greater susceptibility to experimental colitis, manifested as worse histology scores, increased expression of genes encoding proinflammatory cytokines, and the development of intestinal dysbiosis." (PMID 29112157, 2017). "In contrast, another study showed that a lard-based high-fat diet protected against DSS-induced colitis and colitis-associated cancer by increasing gut microbial diversity, including Firmicutes and Clostridium cluster XIVa abundance, upregulating secondary BAs and modulating the VDR pathway." (PMID 39767816, 2024). "Moreover, in a model of DSS-induced colitis, VDR deficiency delayed mucosal healing." (PMID 35057450, 2022). "Although colonic VDR expression in normal mucosa is positively correlated with serum vitamin D levels, VDR expression was significantly depressed in sporadic dysplasia and colorectal cancer tissues compared to that in normal and colitis-associated colorectal cancer tissues." (PMID 30150667, 2018). "Similarly, VDR−/− mice were shown to be more susceptible to Dextran Sodium Sulfate (DSS)-induced colitis due to impaired healing and decreased epithelial junctional complexes, suggesting a role for Vitamin D in the maintenance of the intestinal mucosal barrier." (PMID 26347740, 2015). "In addition, knockdown of the Vitamin D receptor (VDR) gene in Caco-2 cells causes a marked reduction in IEC TJ expression and function, while VDR KO mice are more susceptible to DSS-induced colitis and exhibit more severe inflammation compared to WT littermates." (PMID 24062746, 2013). "This VDR-mediated dysbiosis collectively leads to adverse effects, such as compromised intestinal autophagy and heightened vulnerability to illnesses like colitis, highlighting the essential function of VDR in preserving microbial equilibrium." (PMID 41246320, 2025).